EZH2 (enhancer of zeste 2 polycomb repressive complex 2 subunit)
Diseases named in the same sentence as EZH2 in open-access papers (continued):
Sharing a sentence is not in itself a finding about the gene and the disease.
cancer (continued). "Enhancer of zeste homolog 2 (EZH2) and embryonic ectoderm development (EED) encode components of PRC2 and have been found to play essential roles in cancer initiation, development, progression, metastasis, and drug resistance." (PMID 25829251, 2015). "Inhibiting PRC2 with RNAi or small molecule EZH2 inhibitors reactivated ISG responsiveness, even in SWI/SNF-deficient cancer cells." (PMID 26030458, 2015). "Due to the potential therapeutic value of EZH2 inhibitors in the treatment of cancer, many pharmaceutical companies and academic institutes have recently been involved in the development of small molecule inhibitors of EZH2." (PMID 25923513, 2015). "Multiple pharmaceutical companies are targeting the histone methyltransferase EZH2 for cancer treatment." (PMID 26110843, 2015). "In normal development, EZH2 expression typically declines after birth and remains low in many adult mammalian tissues, with the exception of cancer." (PMID 26304929, 2015). "The identification of these gain of function mutations provided validation for the oncogenic potential of EZH2 and led to a surge of interest in exploring the therapeutic potential of EZH2 as a cancer target." (PMID 26360609, 2015). "Several genetic contexts confer dependency on EZH2 activity in cancer and lead to accumulation of tri-methylated H3K27 (H3K27me3)." (PMID 26360609, 2015). "EZH2, a member of the polycomb-group family, is a specific histone 3 lysine 27 methylt ransferase, and is important in tumorigenesis and cancer progression through epigenetic gene silencing and chromatin remodeling." (PMID 25955318, 2015). "EZH2 contributes to cancer metastasis via regulation of actin-dependent cell adhesion and migration and implicated in EMT and angiogenesis induction." (PMID 25693145, 2015). "Emerging data have demonstrated that EZH2 is aberrantly expressed in various types of human cancers, including breast, brain, colon, gastric, liver, and lung cancers." (PMID 25974088, 2015). "Fourth, EZH2-dependent generation of H3K27me3 mark is necessary for H1.2-induced chromatin compaction observed in cancer cells." (PMID 26581166, 2015). "EZH2 is an oncogene that plays a critical role in cancer development by epigenetically silencing tumor suppressor gene expression." (PMID 26452129, 2015). "Recently, EZH2 contributes to cancer cell invasion and metastasis by down-regulation of E-cadherin through trimethylation of H3K27." (PMID 26336990, 2015). "The enhancer of zeste-homolog 2 (EZH2) is involved in cancer development through gene silencing by trimethylation of lysine 27 of histone 3 (H3K27me3)." (PMID 26553291, 2015). "HOTAIR promotes cancer progression in various ways, including dependents EZH2 to promote cell cycle progression, regulating PTEN methylation and maintaining the stemness of cancer cells." (PMID 25928008, 2015). "EZH2 has been shown to be a critical regulator of epithelial-mesenchymal transition, which is a critical step for initiation of cancer invasion and metastasis." (PMID 25890085, 2015). "Results of the meta-analysis of increased EZH2 expression and clinicopathological features of four types of cancer." (PMID 25974088, 2015). "This included the cell line SUDLH8, which has amplified and highly expressed wild type EZH2 (processed data obtained from the Cancer Cell Line Encyclopedia)." (PMID 26300989, 2015). "Several observations suggest a more pleiotropic and comprehensive role of EZH2 in cancer development." (PMID 26593398, 2015). "Strikingly, despite our enrichment for potential false negatives, we observed a reduction in the proliferation of cancer cells in only one (EZH2) out of seven selected genes." (PMID 25572314, 2015). "This phosphorylation disrupts EZH2 binding with the other PRC2 components SUZ12 and EED, and inhibits EZH2 methyltransferase activity, resulting in inhibition of cancer-cell invasion as well." (PMID 25914884, 2015).
cancer (continued). "When EZH2 signaling pathway is dominant in cancer cells, H3K27me3 levels are high at growth regulatory genes, and H1.2 seems to mainly participate in mediating transcriptional inactivation." (PMID 26581166, 2015). "Although miR-101 based regulation over EZH2 has been addressed independently in human cancers, the interaction between Snail/Slug, miR-101 and EZH2 remains to be systematically investigated." (PMID 25762643, 2015). "Our rescue experiments performed by cotransfection of siEZH2 and siTSSC3 also confirmed the involvement of EZH2 in the mechanism that mediates TSSC3 repression during cancer progression." (PMID 26265454, 2015). "A combined analysis showed that high EZH2 expression predicted poor OS in cancer (HR 1.74, 95% CI: 1.46–2.07; p<0.00001) with significant heterogeneity (I2 = 83.9%)." (PMID 25974088, 2015). "The strong correlation of EZH2 levels with proliferation markers in transcriptome analyses and in our tumorgraft series suggest that high EZH2 expression in cancers is predominantly a consequence of increased cell proliferation rate." (PMID 26637281, 2015). "Elevated EZH2 levels often are directly correlated with advanced metastatic stages of cancer progression and poor prognosis." (PMID 26378043, 2015). "EZH2, a key catalytic subunit of PRC2, functions as a histone methyltransferase that specifically induces histone H3 lysine 27 trimethylation (H3K27me3) to target genes; EZH2 overexpression plays an important role in cancer development and progression." (PMID 26384350, 2015). "This approach identified candidate variants in known cancer genes, including in BCOR, NOTCH2, TET2, NF1, EZH2, and JAK1." (PMID 28721364, 2015). "Enhancer of zeste homolog 2 (EZH2) is a key epigenetic regulator in cancer cell survival, epithelial-mesenchymal transition, and tumorigenesis." (PMID 25890085, 2015). "Only a small number of miRNAs, such as miR-200b, miR-200c and miR-31, have been found as the targets of EZH2 in cancer cells." (PMID 26484567, 2015). "IPA TF analysis predicted activation of EZH2 and MYC, in agreement with their increased expression levels, as well as several other cancer-associated TFs." (PMID 25960784, 2015). "Retinoic acid displaces PcG from its target genes including HOXA1 and RARβ2, whereas ECGC reduces the expression of the PcG components BMI1 and EZH2, slows the proliferation of cancer cells, and promotes apoptosis." (PMID 26339624, 2015). "Using immunohistochemistry, we investigated the distribution pattern of EZH2 in 19 samples of AH and a large cohort of 165 human PA and carcinomas." (PMID 26593398, 2015). "High EZH2 expression (95/120) was detected in the cytoplasm of malignant cells whereas low EZH2 expression (84/120) was observed in the cells in the para-carcinoma tissue." (PMID 26452129, 2015). "Here, we set out to investigate the role of EZH2 in carcinomas using genetic tools in mouse and human model systems." (PMID 26637281, 2015). "In our study, however, we have focused on the role of EZH2 in multiple cancers (instead of different markers for a specific carcinoma)." (PMID 25974088, 2015). "Depletion of EZH2 by siRNA leads to cell cycle arrest of various cancer cells at either G1 or G2 transition." (PMID 25431950, 2014). "The results show that an emodin derivative, NSC745889, has potent anti-cancer effects by down-regulating EZH2 through a proteasome-mediated degradation pathway." (PMID 25431950, 2014). "The deregulation of EZH2 found in cancers includes an over-expression of wild-type protein and a gain-of-function mutation resulting in a switch from tyrosine to histidine at amino acid 641(Y641H); both of which lead to a hyper-trimethylation on H3K27me3." (PMID 25606572, 2014). "Although DZNep is an inhibitor of AdoHcy, in most of cancers it acts through the reduction of EZH2 level and in turn, the re-expression of genes silenced by PRC2 via the demethylation of K27H3." (PMID 25255316, 2014).
cancer (continued). "Overexpression of EZH2 correlates with advanced stages of human cancer progression and poor prognosis." (PMID 24691023, 2014). "Overexpression of EZH2 confers an invasive phenotype on cancer cells via downregulation of tumor suppressor TIMP-3." (PMID 25153722, 2014). "The present study shows that the natural product derivative NSC745885 efficiently depletes EZH2, resulting in the inhibition of cell growth in various cancer cells." (PMID 25431950, 2014). "All these oncogenic effects of EZH2 on cancer cells make it a perfect target of new anti-cancer drug development." (PMID 25431950, 2014). "Small molecule inhibitors of histone methyltransferases are emerging and a number of novel EZH2 inhibitors are under preclinical evaluation in other types of cancer." (PMID 24575771, 2014). "For example, PRC2 target genes are commonly hypermethylated in cancer, and EZH2 is up-regulated in various cancer subtypes." (PMID 25473433, 2014). "Further investigation of the detailed mechanisms of how NSC745885 differentially activates the ubiquitination system to regulate EZH2 protein stability in cancer cells is warranted." (PMID 25431950, 2014). "G9a and EZH2 are up-regulated in a number of different cancers and seem to be required for the maintenance of the malignant phenotype." (PMID 24652950, 2014). "Studies have found that the expression of the EZH2 gene in cancer was significantly higher than in paraneoplastic or normal tissue." (PMID 25226601, 2014). "The observation that in RMS DZNep induces myogenic differentiation instead of apoptosis, the general effect that DZNep has in other human cancer, suggests that its inhibition toward EZH2 is quite specific being pro-differentiative." (PMID 24575771, 2014). "KLF2 promoter is also an EZH2 target gene in many cancers and recently shown to be hyper-methylated by DNMT1 in endothelial cells." (PMID 25115397, 2014). "An inhibitor of EZH2, 3-Deazaneplanocin (DZNep), is hence proposed to be tested as a method of epigenetic cancer therapy." (PMID 25606572, 2014). "Our results provide the first evidence that, in aggressive EC cells, miR-101 governs multiple malignant phenotypes including proliferation, migration, invasion and cancer stemness, at least partly via downregulating the expression of EZH2, MCL-1 and FOS." (PMID 25153722, 2014). "In particular, Ezh2 inhibition was recently found as a therapeutic strategy for Ezh2-mutant cancers." (PMID 25517911, 2014). "It is reported that EZH2 serves as a histone methyl transferase involved in gene silencing, and disruption of EZH2 expression can lead to cancer." (PMID 25036033, 2014). "Unlike EZH1, which is present in both dividing and differentiated cells, EZH2 expression is specific to actively dividing cells, making it an attractive therapeutic target for cancer." (PMID 24971229, 2014). "Over-expression of EZH2 in cancer cells attenuated effects of NSC745885, suggesting that down-regulation of EZH2 was responsible for growth inhibition of NSC745885." (PMID 25431950, 2014). "In the present study, the cell-based platform with GFP-EZH2 expression cancer cells is used to screen multiple emodin derivatives that can target EZH2 for new drug identification." (PMID 25431950, 2014). "Taken together, these findings suggest that the development of EZH2 inhibitors for cancer chemotherapy will benefit from a continued understanding of the multiple, distinct roles that EZH2 plays in development and cell differentiation." (PMID 24867641, 2014). "EZH2, a human H3K27 KMT which is a catalytic component of the PRC2 complex, is an oncogene overexpressed in many cancers and is associated with poor prognosis in breast and prostate cancers." (PMID 24859458, 2014). "Similar findings have also been observed with A677G and A687V mutant EZH2, though these are far less prevalent in cancer." (PMID 24622842, 2014).
cancer (continued). "Knockdown of EZH2 expression in cancer cells induced cellular senescence, apoptosis and mesenchymal-to-epithelial transition features." (PMID 25153722, 2014). "These clearly demonstrate that targeting the EZH2 protein itself instead of its enzyme activity will be a more efficient strategy for developing anti-cancer medicine." (PMID 25431950, 2014). "Positive EZH2 status was defined as nuclear immunohistochemical staining in at least 10% of invasive cancer cells." (PMID 25051981, 2014). "Different mechanisms have been described to explain the pro-metastatic activity of the histone methyltransferase EZH2 in various cancer types, but little is known about its role regarding CRC." (PMID 25549357, 2014). "A prominent example is EZH2, a protein that is frequently up-regulated in cancer and catalyzes the methylation of H3K27 as part of the large multiprotein repressive complex PRC2 (polycomb repressive complex 2)." (PMID 25322458, 2014). "Another interesting finding here is that NSC745885 overcomes multiple drug resistances with efficient EZH2 depletion of MGHU1R cancer cells." (PMID 25431950, 2014). "This makes the inhibition of histone-modifying enzymes, in particular EZH2, an important target in the development of cancer therapeutics for many different cancer types." (PMID 24587223, 2014). "The chromatin regulator enzyme EZH2, which regulates survival and metastasis of cancer cells, was found to be a direct target of miR-26a." (PMID 24999473, 2014). "Since EZH2 is a histone methyltransferase, inhibition of its enzyme activity has been initially considered to be an effective way for cancer treatment." (PMID 25431950, 2014). "EZH2 is often overexpressed in cancer cells and leads to transcriptional repression by tri-methylation of histone 3 lysine 27 (H3K27me3)." (PMID 25322458, 2014). "For example, co-expression of EZH2 and BMI1 was reported to be associated with poor prognosis in various cancers." (PMID 25243792, 2014). "Previous observations indicate that EZH2 is a perfect candidate for developing the next novel anti-cancer medicine." (PMID 25431950, 2014). "The functional consequence of increased EZH2 expression in cancer tissues includes the silencing of genes that promote differentiation and restrain proliferation." (PMID 25159232, 2014). "Overexpression of EZH2 can silence important tumor suppressor genes leading to increased invasiveness of many types of cancers." (PMID 24587223, 2014). "Previous studies reported that EZH2 is a tumorigenic gene that correlates with cancer progression and a poor prognosis." (PMID 25081869, 2014). "The present study provides evidence that NSC745885 efficiently depletes EZH2 in cancer cells, which has the advantage of overcoming the EZH2-mediated drug resistance of cancer stem cells." (PMID 25431950, 2014). "Our previous studies have shown that EZH2 protein is overexpressed in PGCCs using iTRAQ-based proteomic analysis comparing PGCCs and diploid cancer cells." (PMID 25025074, 2014). "BMI1 and EZH2 levels are elevated in several types of cancer and there is increasing evidence that they promote tumor progression by supporting cellular self-renewal and proliferation, while blocking differentiation." (PMID 25249625, 2014). "Here we have shown for the first time that, in cancer cells, miR-1246 is a common target of EZH2 inhibitors and that miR-302a and miR-4448 are activated by SAHA and DZNep." (PMID 24861464, 2014). "Growing evidence suggests a strong link of enhancer of zest homolog-2 (EZH2), a polycomb repressor complex-2 protein, to oncogenesis and to cancer-specific gene silencing." (PMID 25216513, 2014). "The effects of NSC745885 on EZH2 expression levels in different cancer cell lines were further investigated." (PMID 25431950, 2014). "Increasing evidence demonstrates that EZH2 is not only aberrantly expressed in several types of human cancers, but often behaves as a molecular biomarker of poor prognosis." (PMID 24575771, 2014).
cancer (continued). "On the other hand, enzymes that deposit repressive histone marks, such as the H3K9 trimethylases SETDB1 or SUV39H1/2, and the H3K27 trimethylase EZH2 are overexpressed in most cancer types studied." (PMID 25484917, 2014). "Overexpression of EZH2 has been found in many cancers and the expression level is correlated with tumor progression and poor prognosis." (PMID 25216513, 2014). "Recent studies have indicated that Ring1B and EZH2 are required and dysregulated in several types of human cancer." (PMID 25431952, 2014). "In human cancers, miR-137 can modulate the expression of a multitude of genes, including EZH2, FMNL2, and Paxillin." (PMID 24970808, 2014). "EZH2 was previously shown to be overexpressed in cancers, and EZH2 expression levels correlated with aggressiveness, metastasis, and a poor prognosis." (PMID 25081869, 2014). "One important role of EZH2 in cancer is the epigenetic repression of tumor suppressor genes by histone modification and promoter methylation." (PMID 25226601, 2014). "Three major members of the MAPK family, the p38 kinase, JNK and ERK were stimulated to down-regulate the enhancer of zeste homolog 2 (EZH2) gene overexpression leading to proliferation of the cancer cells." (PMID 25566531, 2014). "EZH2 is frequently overexpressed and correlates with poor prognosis in many human cancers, as well as in UCB." (PMID 24093096, 2013). "Overexpression or activating mutations of EZH2, the catalytic component of the PRC2 complex, are linked to hyper-trimethylation of lysine 27 of histone H3 (H3K27me3) in many cancers." (PMID 24367611, 2013). "The current study initiated from investigations on the role of the EZH2 locus in the proliferative response, as previous reports implicated overexpression of this HMT during neoplastic transformation in a variety of cancers." (PMID 23448518, 2013). "Collectively, our findings suggest that epigenetic silencing of DLC1 is involved in the pro-metastatic function of EZH2 in human cancers." (PMID 23826380, 2013). "Cancer stem cells can express both EZH2/H3k27me3 and Nanog, and the epigenetic balance between these factors determines the further fate of the cells." (PMID 24313165, 2013). "We also sought to gain insight into their biological function by analyzing their effect on cell proliferation, one of the best-characterized functions attributed to the EZH2 locus in normal morphogenesis and cancer." (PMID 23448518, 2013). "Cytogenetic studies, as well as next generation sequencing of various cancer genomes, have demonstrated recurrent translocations and/or coding mutations in a large number of lysine methyltransferases, including MMSET, EZH2, and MLL family members." (PMID 24202337, 2013). "EZH2 and HDACs were recently identified as critical histone modifiers of deregulated miRNAs in cancer and can be recruited to a miRNA promoter by transcription factors such as MYC." (PMID 24261995, 2013). "Recently, many intronic RNA sequences capable of binding the PRC2 core component EZH2 have been detected in human cancer cells." (PMID 23990798, 2013). "Overexpression of EZH2 has been correlated with advanced stages of human cancer progression and poor prognosis." (PMID 24040354, 2013). "Through its catalytic role in the PRC2 complex, EZH2 normally functions to epigenetically silence genes during development, however, it aberrantly silences genes in human cancers." (PMID 23967231, 2013). "Previous reports have established that EZH2 is aberrantly overexpressed in a wide range of cancer types including breast, prostate, lung cancer and so forth." (PMID 24345883, 2013). "For let-7e-3p, cancer-associated genes such as MAPK1 and EZH2 were among the negatively correlated genes, and PURA, ERCC1 and MAPT were among the positively correlated ones." (PMID 24257477, 2013). "The functional roles of H3K27me3 and EZH2 in cancer progression are incompletely understood, as EZH2 has been proposed to both promote and oppose cancer formation and progression." (PMID 23826629, 2013).